VIRMA (vir like m6A methyltransferase associated)
Diseases named in the same sentence as VIRMA in open-access papers (continued):
Sharing a sentence is not in itself a finding about the gene and the disease.
ovarian carcinoma (12 papers, 2020 to 2025). A malignant neoplasm originating from the surface ovarian epithelium. "The expression of VIRMA in different types of ovarian cancers in the Oncomine database is different and the highest in ovarian serous adenocarcinoma." (PMID 33731118, 2021). "VIRMA protein was found to be downregulated in ovarian cancer tissues than normal tissues and positively correlated with worse OS." (PMID 33731118, 2021). "In this context, “readers” such as METTL3 and VIRMA have been associated with apoptosis inhibition, migration, and invasion in ovarian cancer, while FTO leads to reduced “stemness” in ovarian cancer cell lines and YBX1 renders malignant cells susceptible to the cytotoxic effects of cisplatin." (PMID 41301911, 2025). "In addition, VIRMA has also been found to be highly expressed in ovarian cancer tissues, and its expression level is negatively correlated with the survival rate." (PMID 38343637, 2024). "WTAP and VIRMA are substantially expressed in ovarian cancer and correlate with prognosis." (PMID 37194218, 2023). "According to risk score models, patients with ovarian cancer who had low VIRMA or high HNRNPA2B1 expression had prolonged half survival, and the constructed miRNA-m6A regulator (VIRMA, IGF2BP1, HNRNPA2B1)-target gene regulatory network could predict the prognosis of OC patients." (PMID 37194218, 2023). "In conclusion, m6A RNA methylation regulators are vital participants in ovarian cancer pathology; and IGF2BP1, VIRMA, and ZC3H13 mRNA levels are valuable factors for prognosis prediction and treatment strategy development." (PMID 32950970, 2020). "Although the specific mechanism of action has not been clarified, some researchers have considered that VIRMA may be related to the WNT signaling pathway process in ovarian cancer." (PMID 38343637, 2024).
lung adenocarcinoma (11 papers, 2020 to 2024). A carcinoma that arises from the lung and is characterized by the presence of malignant glandular epithelial cells. "Even with these insights, the triggering of KIAA1429 (also called VIRMA) and its role in lung adenocarcinoma (LUAD) is mostly unclear." (PMID 38717936, 2024).
lung carcinoma (11 papers, 2021 to 2025). "VIRMA was found to enhance the activity of the PI3K/AKT pathway by upregulating the m6A modification of the tumor suppressor ARHGAP30, promoting lung cancer cell proliferation and migration." (PMID 40723784, 2025).
glioma (10 papers, 2019 to 2025). A benign or malignant brain and spinal cord tumor that arises from glial cells (astrocytes, oligodendrocytes, ependymal cells). "According to these findings, RP2 may be correlated with m6A modification in glioma, and the combined effect of METTL14, VIRMA, ALKBH5, YTHDC2 and METTL3 may eventually affect the progression and poor prognosis of glioma." (PMID 37602882, 2023).
non-small cell lung carcinoma (8 papers, 2021 to 2025). A group of at least three distinct histological types of lung cancer, including non-small cell squamous cell carcinoma, adenocarcinoma, and large cell carcinoma. "In non-small cell lung cancer (NSCLC), VIRMA is highly expressed and associated with patient prognosis." (PMID 40959082, 2025).
prostate carcinoma (8 papers, 2020 to 2024). A carcinoma that arises from epithelial cells of the prostate gland. "VIRMA was upregulated in four major urogenital neoplasms: including kidney cancer, bladder cancer, prostate cancer and testicular cancer." (PMID 33731118, 2021). "Moreover, VIRMA downregulation attenuated the aggressive phenotype of prostate cancer cells by reducing the stability and abundance of oncogenic lncRNAs through an overall reduction in m6A levels." (PMID 37421455, 2023). "In prostate cancer, the high expression of VIRMA was correlated with cancer progression." (PMID 33731118, 2021). "According to a recent study, VIRMA is up-regulated in prostate cancer." (PMID 32612834, 2020). "Of note, VIRMA and m6A methylation reader YTHDF3 were upregulated and showed a strong positive correlation in prostate cancer and TGCTs, as they jointly facilitated poor prognosis." (PMID 33731118, 2021). "VIRMA and YTHDF2 play vital roles in prostate cancer, the second most common diagnosed cancer in men." (PMID 32612834, 2020). "Another study demonstrated that knockdown of VIRMA could decrease the stability of CCAT1 and CCAT2 lncRNA in an m6A-dependent manner to regulate MYC transcription, promoting progression of prostate cancer." (PMID 33731118, 2021). "VIRMA knockdown could decrease the m6A levels and stability of CCAT1 and CCAT2 lncRNA in prostate cancer." (PMID 33731118, 2021).
colon adenocarcinoma (6 papers, 2021 to 2025). "VIRMA is up-regulated in colon adenocarcinoma, and its silencing in colonic adenocarcinoma cell lines has been shown to inhibit tumor growth by blocking the HIF-1 signaling pathway." (PMID 40102715, 2025). "In colon adenocarcinoma (COAD), silencing VIRMA blocked the HIF-1 signaling pathway, inhibiting the proliferation, migration, invasion, and proptosis of colon cancer cells." (PMID 40723784, 2025).
bladder cancer (5 papers, 2021 to 2026). "In bladder cancer, VIRMA seems to be a useful marker, as it is amongst the most commonly deregulated and significantly upregulated in high grade tumors." (PMID 33731118, 2021). "A functional role of VIRMA is confirmed in knockdown experiments that reveal reduced 3'-UTR methylation and oncogenic phenotypes of bladder cancer cells." (PMID 41872550, 2026). "VIRMA was significantly upregulated in non-papillary tumors (the most aggressive, more prone to progress and metastasize) among different types of bladder cancers." (PMID 33731118, 2021).
Ewing sarcoma (5 papers, 2023 to 2025). A small round cell tumor that lacks morphologic, immunohistochemical, and electron microscopic evidence of neuroectodermal differentiation. "CRISPR-Cas9-mediated knockout of VIRMA has shown anti-tumor effects in Ewing sarcoma models." (PMID 40723784, 2025).
seminoma (5 papers, 2019 to 2023). A radiosensitive malignant germ cell tumor found in the testis (especially undescended), and extragonadal sites (anterior mediastinum and pineal gland). "KIAA1429 (VIRMA) regulated the response of seminoma to cisplatin by disturbing DNA damage, and tumor sensitivity to cisplatin was increased after KIAA1429 knockdown." (PMID 37264402, 2023). "Of relevance, higher VIRMA and YTHDF3 expression levels were observed in the seminoma-like TCam-2 cells compared to the analyzed NS cell lines, in line with our previous observations in primary tissues in silico analysis." (PMID 34446080, 2021).
thyroid cancer (5 papers, 2021 to 2024). "VIRMA exhibits diminished expression in kidney renal papillary cell carcinoma, thyroid carcinoma, prostate adenocarcinoma, and uterine corpus endometrial carcinoma." (PMID 38577917, 2024).
cholangiocarcinoma (4 papers, 2023 to 2026). A carcinoma that arises from the intrahepatic biliary tree (intrahepatic cholangiocarcinoma) or from the junction, or adjacent to the junction, of the right and left hepatic ducts (hilar cholangiocarcinoma). "Secreted CCL3 from hepatocytes, enhances cancer spread by triggering VIRMA and its key downstream target SIRT1, which drives the metastasis of intrahepatic cholangiocarcinoma." (PMID 39941858, 2025).
diffuse large B-cell lymphoma (4 papers, 2023 to 2025). "However, the function of m6A modification mediated by KIAA1429 [alias virus-like m6A methyltransferase-associated protein (VIRMA)] during the progression of diffuse large B-cell lymphoma (DLBCL) remains undefined." (PMID 37076815, 2023).
nasopharyngeal carcinoma (4 papers, 2023 to 2025). A carcinoma arising from the nasopharyngeal epithelium. "VIRMA can up-regulate the expression of E2F7 and maintain the stability of E2F7 mRNA, promoting the occurrence and metastasis of nasopharyngeal carcinoma." (PMID 41256854, 2025). "VIRMA enhances mRNA stability and transactivates integrin subunit alpha (ITGA2), promoting nasopharyngeal carcinoma progression." (PMID 39006762, 2024).
pancreatic cancer (4 papers, 2021 to 2022). "Furthermore, pancreatic cancer patients with lower METTL3, METTL14, RBMX, FTO, ALKBH5, YTHDF1, and YTHDC1 mRNA expression levels or higher VIRMA, HNRNPA2B1, EIF3A, IGF2BP1, IGF2BP2, and IGF2BP3 mRNA expression levels had significantly poorer OS (P < 0.05)." (PMID 34330301, 2021). "After treated with gemcitabine, only METTL14 was significantly increased in all six pancreatic cancer cell lines, but not METTL3, WTAP, VIRMA, FTO or ALKBH5." (PMID 34458141, 2021).
cervical cancer (3 papers, 2022). A primary or metastatic malignant neoplasm involving the cervix. "We revealed higher levels of ZC3H13, WTAP, HNRNPC, YTHDF3, and VIRMA were significantly associated with worse outcomes in CESC (HR > 1, blue background), while YTHDC1, YTHDF1 were protective factors of cervical cancer (HR < 1, orange background)." (PMID 35581263, 2022). "YTHDC1 and YTHDF1 have anti-cancer effects in cervical cancer, while ZC3H13, WTAP, HNRNPC, YTHDF3 and VIRMA have tumor-promoting effects in cervical cancer." (PMID 35581263, 2022).
intrahepatic cholangiocarcinoma (3 papers, 2023 to 2025). A carcinoma that arises from the intrahepatic bile duct epithelium in any site of the intrahepatic biliary tree. "In intrahepatic cholangiocarcinoma (ICC), hepatocyte-secreted CCL3 promotes metastasis via VIRMA-mediated m6A modification, which upregulates SIRT1 and drives tumor progression." (PMID 40034695, 2025). "VIRMA can maintain the stability of TMED2 and PARD3B through m6A HuR mediation, activate the Akt/GSK/β- catenin and MEK/ERK/Slug signaling pathways, thereby promoting further deterioration of intrahepatic cholangiocarcinoma (ICC)." (PMID 41256854, 2025).
melanoma (3 papers, 2020 to 2021). A malignant, usually aggressive tumor composed of atypical, neoplastic melanocytes. "RBM15, VIRMA, IGF2BP3, and YTHDF3 were frequently overamplified in melanoma patients, while VIRMA displayed missense mutations with unknown significance." (PMID 34446007, 2021).
Obesity (3 papers, 2021 to 2025). Accumulation of substantial excess body fat. "Interestingly, we find that gene expression of VIRMA associates with obesity both in SAT and OVAT showing lower expression in obesity." (PMID 34950106, 2021). "Furthermore, in human cohorts, the study found that the writers WTAP and VIRMA, the eraser ALKBH5, and reader proteins such as YTHDF1, YTHDF2, and YTHDC1 are associated with obesity by comparing gene expression of m6A regulators in adipose tissue between individuals with obesity and lean controls." (PMID 40428320, 2025). "In adipose tissue we observed that several m6A regulators (WTAP, VIRMA, YTHDC1 and ALKBH5) correlate with obesity and clinical variables." (PMID 34950106, 2021). "Our results suggest a role for VIRMA in adipose tissue biology and metabolism, particularly in SAT, and further functional studies are required to investigate the role of this m6A writer in obesity." (PMID 34950106, 2021).
ovarian serous cystadenocarcinoma (3 papers, 2020 to 2023). A malignant serous cystic epithelial neoplasm arising from the ovary. "The expression of YTHDF1, HNRNPC, IGF2BP1, VIRMA, and HNRNPA2B1 was significantly positively correlated with the ovarian serous cystadenocarcinoma (OV) tumor stem cell score (based on DNA methylation) (DNAss)." (PMID 34150845, 2021).
papillary thyroid carcinoma (3 papers, 2021 to 2022). "Univariate and multivariate analyses demonstrated that the risk score of VIRMA is an independent prognostic factor in papillary thyroid carcinoma, indicating that VIRMA might act as a tumor suppressor." (PMID 33731118, 2021). "Studies on VIRMA in papillary thyroid carcinoma were from TCGA database, which need further exploration of clinical confirm and the underlying molecular mechanisms." (PMID 33731118, 2021). "VIRMA was downregulated and predicted better OS in papillary thyroid carcinoma." (PMID 33731118, 2021).
prostate adenocarcinoma (3 papers, 2021 to 2024). "VIRMA was more lowly expressed in uterine corpus endometrial carcinoma (UCEC), thyroid carcinoma (THCA), prostate adenocarcinoma (PRAD) and kidney renal papillary cell carcinoma (KIRP)." (PMID 33731118, 2021).
glioblastoma (2 papers, 2022 to 2024). The most malignant astrocytic tumor (WHO grade IV). "KIAA1429, also known as VIRMA, is consistently upregulated in glioblastoma and negatively correlated with the response to anti-cancer drugs, suggesting its role in drug resistance and tumor progression." (PMID 38474421, 2024).
bile duct cancer (1 paper, 2023). "We further showed that CCL3 promoted the metastasis of intrahepatic bile duct cancer cells by regulating VIRMA/SIRT1 pathway in the orthotopic ICC tumor model." (PMID 36691046, 2023).
colon cancer (1 paper, 2023). "Finally, to identify the key biological function of m6A/m5C/m1A regulators in colon cancer, we performed immunohistochemical staining and RT-qPCR to screen two key biomarkers (VIRMA and DNMT3B)." (PMID 37421455, 2023). "However, the role of VIRMA in colon cancer still needs to be further explored." (PMID 37421455, 2023). "The results indicated that VIRMA and DNMT3B were significantly higher in colon cancer tissue, which was consistent with the previous analysis." (PMID 37421455, 2023). "Next, we further explored the mRNA expression levels of VIRMA and DNMT3B in 10 pairs of colon cancer and normal tissues with RT-qPCR." (PMID 37421455, 2023). "The results indicated that VIRMA and DNMT3B had higher mRNA expression levels in colon cancer tissue, which was consistent with the protein level results." (PMID 37421455, 2023). "Finally, we validated m6A/m5C/m1A regulators at the protein and mRNA expression levels, which further identified that VIRMA and DNMT3B played vital roles in colon cancer." (PMID 37421455, 2023). "Finally, we validated that the mRNA and protein expression of VIRMA and DNMT3B increased in colon cancer tissues." (PMID 37421455, 2023). "Therefore, we identified that VIRMA and DNMT3B could play vital roles in colon cancer." (PMID 37421455, 2023).
COVID-19 (1 paper, 2022). A disease caused by infection with severe acute respiratory syndrome coronavirus 2. "We observed that RBM15B, HNRNPA2B1, and VIRMA may be protective factors in the development of COVID-19, and the opposite performance was found in ELAVL1, RBM15, FMR1, IGFBP3, and METTL3." (PMID 35655464, 2022). "COVID-19 patients with high expression levels of FTO tend to display high levels of METTL3, METTL16, RBM15B, or VIRMA." (PMID 35655464, 2022). "Similarly, the specific role of VIRMA, ELAVL1, and FMR1 in COVID-19 was mentioned in several studies." (PMID 35655464, 2022).
endometrial cancer (1 paper, 2021). Primary or metastatic malignant neoplasm involving the endometrium (mucous membrane that lines the endometrial cavity). "In endometrial cancer patients, higher HNRNPC, YTHDC2, WTAP, VIRMA, IGF2BP3, and HNRNPA2B1 expression is closely associated with worse outcomes and advanced stage." (PMID 34616742, 2021). "More recently, the levels of YTHDC2, HNRNPC, and VIRMA were suggested to be negatively correlated, whereas WTAP was positively correlated, with MHC molecules in endometrial cancer." (PMID 34616742, 2021).
kidney cancer (1 paper, 2021). Primary or metastatic malignant neoplasm involving the kidney. "In kidney cancer, the VIRMA expression could be a biomarker to discriminate these RCC subtypes, and was associated with OS and DFS." (PMID 33731118, 2021).
metastatic prostate carcinoma (1 paper, 2020). A carcinoma that arises from the prostate gland and has spread to other anatomic sites. "Remarkably, the higher percentage of amplification, and consequently expression, disclosed for VIRMA compared to the other core subunits might be explained by VIRMA genomic location at 8q chromosome, which is commonly altered in locally advanced and metastatic prostate cancers." (PMID 32218194, 2020).
myocardial ischemia (1 paper, 2024). A disorder of cardiac function caused by insufficient blood flow to the muscle tissue of the heart. "Interestingly, contrary to previous myocardial ischemia-reperfusion research, VIRMA (also known as KIAA1429) also participates in the binding of DGCR8 to pri-miR143-3p, in which the target gene is DEAD-box helicase 6 (DDX6)." (PMID 38988324, 2024).
osteoarthritis (1 paper, 2023). A noninflammatory degenerative joint disease occurring chiefly in older persons, characterized by degeneration of the articular cartilage, hypertrophy of bone at the margins and changes in the synovial membrane. "Among them, VIRMA and LRPPRC were the most highly correlated m6A regulators expressed in all samples and osteoarthritis samples and showed a positive correlation, whereas VIRMA and RBM15B were the most negatively correlated." (PMID 36777725, 2023).
testicular cancer (1 paper, 2020). A primary or metastatic malignant neoplasm that affects the testis. "The m6A-related enzymes VIRMA and YTHDF3 have been implicated in testicular cancer." (PMID 32765970, 2020).